CCL22 (C-C motif chemokine ligand 22)
Diseases named in the same sentence as CCL22 in open-access papers (continued):
Sharing a sentence is not in itself a finding about the gene and the disease.
cutaneous melanoma (1 paper, 2019). A primary melanoma arising from atypical melanocytes in the skin. "This study analyzed baseline serum levels of CXCL5, CXCL10, and CCL22 in 46 cases of advanced cutaneous melanoma treated with nivolumab." (PMID 31080803, 2019). "Characteristics and serum levels of CXCL5, CXCL10, and CCL22 in patients with cutaneous melanoma." (PMID 31080803, 2019).
Delusion (1 paper, 2020). A delusion is a fixed false belief held despite evidence to the contrary. "FEP patients at baseline showed an association between serum CCL22 levels and hallucinations, conceptual disorganization, and worse verbal performance, but not with delusions, blunted affect, visuomotor performance or SOFAS." (PMID 32179746, 2020).
diabetes (1 paper, 2025). "In this study, we have identified a group of APMB-specific analytes (IL-10, CXCL1, IL-12p40, IL-13, CCL22, CCL4, IL-17A, and TGFα) that correlates with several clinical phenotypes associated with more severe SAB (diabetes, dialysis dependence, metastatic infection, and cardiac vegetation)." (PMID 39966757, 2025). "Additionally, CXCL1, CCL22 and IL-17A significantly differed between APMB and ARMB when correlated with diabetes, dialysis, metastatic infection, or cardiac vegetation." (PMID 39966757, 2025).
diarrhoea (1 paper, 2022). "Some of the DEGs in diarrhoea-susceptible sheep, enriched in GO terms and sub-network analysis, included IL-6, LOC101121216 (serum amyloid A), SIGLEC1, CHI3L1, S100A9, CD14, CD68, CD86, Ovar-DRB1, IL1RL1, LOC101103238 (CXCL5), CCL22 and IL1RN." (PMID 35576023, 2022).
disc degeneration (1 paper, 2025). "A recent study demonstrated that a combination of age, C-reactive protein and CCL22 plasma levels could efficiently predict the recovery of patients who underwent spine surgery to treat disc degeneration." (PMID 39930483, 2025).
emphysema (1 paper, 2023). "The levels of inflammatory cytokines related to type 2 inflammation (including CCL11, CCL17, and CCL22) were significantly elevated in the emphysema model compared to the controls." (PMID 37816708, 2023).
endometrial tumor (1 paper, 2024). "Immunohistochemical staining of CCL22 revealed three different areas of expression: 1) the epithelial, endometrial tumor cells showed uniform levels of CCL22; 2) intratumoral and peritumoral stromal or myometrial areas (S/M) were CCL22-positive (CCL22+) without association to specific cells." (PMID 39232378, 2024).
enterovirus infection (1 paper, 2020). "After enterovirus infections, the cytokine profile showed an upregulation of Th1- and Th17-related cytokines and a decreased activation of CCL22, which is a chemokine derived from dendritic cells and associated with Th2 deviation." (PMID 33643278, 2020). "The cytokine profile after enterovirus infections was also different, showing an upregulation of Th1 and Th17 responses, and decreased activation of CCL22, which is a chemokine derived from dendritic cells and associated with Th2 deviation." (PMID 33643278, 2020). "In contrast, in the infants with enterovirus infection increased levels of CXCL10 (IP-10), which is related to Th1 immunity and IL-17 were found after the infection, while CCL4 (MIP-1β) and CCL22 (MDC), remained decreased after enterovirus infection." (PMID 33643278, 2020).
focal segmental glomerulosclerosis (1 paper, 2023). A renal disorder characterized by sclerotic lesions in the glomeruli. "CCL22 levels were significantly elevated in SRNS (92.2 ± 157.0 pg/ml), but the difference seemed to be attributed to the specific type of pathology, such as Minimal change disease (MCD) (127.4 ± 206.7 pg/ml) and focal segmental glomerulosclerosis (FSGS) (114.8 ± 22.0 pg/ml)." (PMID 37744450, 2023).
gastroduodenitis (1 paper, 2016). "For example, in H. pylori positive gastroduodenitis we demonstrate increased serum levels of chemoattractants for mononuclear lymphocytes, such as CXCL10, CCL22, and CXCL16." (PMID 28018296, 2016).
Granuloma (1 paper, 2013). A compact, organized collection of mature mononuclear phagocytes, which may be but is not necessarily accompanied by accessory features such as necrosis. "MMP3, CCL20 and CCL22 showed significance increase in tuberculoid as compared to the lepromatous lesions adding support to the increased lymphocytes seen in BT granulomas." (PMID 23936569, 2013).
Graves disease (1 paper, 2025). Graves' disease is an autoimmune disorder that leads to overactivity of the thyroid gland (hyperthyroidism).It is caused by an abnormal immune system response that causes the thyroid gland to produce too much thyroid hormones. "The shift from Th1 to Th2 immune response, marked by CCL2 and CCL22, is observed in advanced stages of PsA and Graves’ disease." (PMID 40863211, 2025).
heart failure (1 paper, 2024). Inability of the heart to pump blood at an adequate rate to meet tissue metabolic requirements.
helminthes infection (1 paper, 2018). "Our observations of CCL22-mediated significant expansion of Tregs in the spleens of mice was corroborated with previous reports documenting the expansion of Tregs within 3–7 days of helminthes infection." (PMID 29483912, 2018).
idiopathic nephrotic syndrome (1 paper, 2023). Nephrotic syndrome for which no cause has been identified. "In conclusion, this study has demonstrated an association between serum concentrations of CCL22 and Leptin, measured prior to steroid therapy, and steroid resistance in childhood idiopathic nephrotic syndrome." (PMID 37744450, 2023). "The present study focused on the serum concentrations of CCL22 and Leptin in patients with idiopathic nephrotic syndrome." (PMID 37744450, 2023).
immunotoxicity (1 paper, 2018). "Results from the sparse PLS models selecting both exposures and proteins suggest a swimming-induced immunotoxicity through decreased level of IL-8, VEGF, CCL22, CCL11, CRP and CXCL10, and increased levels of IL-1ra, which antagonises the proinflammatory IL-1." (PMID 29563153, 2018).
interstitial lung disease (1 paper, 2024). A diverse group of lung diseases that affect the lung parenchyma. "Random forest analysis showed that the underexpression of macrophage-derived chemokine CCL22, which has been implicated in interstitial lung disease pathogenesis, had the highest variable importance that was associated with persistent CT abnormalities in our cohort." (PMID 39324144, 2024).
intestinal cancer (1 paper, 2023). "Cochrane’s Q test did not provide evidence of heterogeneity between CCL14 (p = 0.768, p = 0.808), CCL22 (p = 0.502), CCL28 (p = 0.175), CXCL12 (p = 0.530) and CXCL14 (p = 0.534) and intestinal cancer." (PMID 38075694, 2023).
Intestinal tumors (1 paper, 2026). "Intestinal tumors in myeloid Mir34a-deficient mice showed elevated expression of several known Mir34a target mRNAs, including Csf1r, Pd-l1, Mmp9, Ccl22, and c-Myc." (PMID 42140945, 2026).
Lewis lung carcinoma (1 paper, 2024). "In Lewis lung carcinoma, miR-545-3p recruits CD4+CD25+ regulatory T cells via CCL22 to inhibit tumor growth." (PMID 39027151, 2024).
metastatic tumors (1 paper, 2015). "Quantitative RT-PCR further confirmed that ICAM-1 deficiency significantly upregulated mRNA levels of IL-10, TGF-β, chemokine (C–C motif) ligand 17 (CCL17), CCL22 (M2-specific cytokines or chemokines) in hepatic metastatic tumors." (PMID 26068788, 2015).
monocytic leukemia (1 paper, 2021). "THP-1 cells, a cell line derived from a patient with monocytic leukemia, were a reasonable candidate given their origins in the myeloid lineage and known production of CCL22 in response to a variety of stimuli." (PMID 34781732, 2021).
morbid obesity (1 paper, 2023). An excess of body weight, normally defined as an individual with a body mass index greater than 35 or a body weight greater than one hundred percent of ideal body weight. "The aim of this study was to investigate the role of chemokine receptor CCR4 and its ligands CCL17 and CCL22 in human morbid obesity." (PMID 37124725, 2023). "Similarly, patients with morbid obesity showed systemic CCL22 levels higher than controls (median 186.6 pg/mL, range 30.3–420.8 pg/mL in patients vs. median 136.8 pg/mL, range 68.2–200.3 pg/mL in controls, p<0.001)." (PMID 37124725, 2023).
mucinous cystadenocarcinoma (1 paper, 2015). An invasive adenocarcinoma characterized by cystic changes and the presence of malignant glandular cells which contain intracytoplasmic mucin. "Unexpectedly, the highest concentrations of CCL22 were found in the PF of women with endometrioid cystadenocarcinoma and in plasma of women with mucinous cystadenocarcinoma." (PMID 25647263, 2015).
mycosis fungoides (1 paper, 2022). Classical mycosis fungoides is the most common type of mycosis fungoides (MF), a form of cutaneous T-cell lymphoma, and is characterized by slow progression from patches to more infiltrated plaques and eventually to tumors. "Notably, CD163+CD206+ TAMs produce M2 macrophage-related chemokines such as CCL22 by the stimulation of IL-4 in cancer stroma, which leads to recruitment of CCR4+ lymphoma cells to develop tumor formation in mycosis fungoides." (PMID 35409404, 2022). "Notably, since CCL17 and CCL22 are ligands of CCR4, the major chemokine receptor expressed in CTCL cells, the production of these chemokines from TAMs could result in tumor formation in mycosis fungoides in the tumor stage." (PMID 35409404, 2022).
myeloid leukemia (1 paper, 2022). A clonal proliferation of myeloid cells and their precursors in the bone marrow, peripheral blood, and spleen. "In our study, IL-4 could induce the expression of M2 markers including IL-10, TGF-β, and CD163 as well as some chemokines including CCL-17 and CCL-22 in human myeloid leukemia mononuclear THP-1 cells." (PMID 35996149, 2022).
nephrotic syndrome (1 paper, 2023). A collection of symptoms that include severe edema, proteinuria, and hypoalbuminemia; it is indicative of renal dysfunction. "This study demonstrated the potential of CCL22 and Leptin to predict steroid resistance in the early stages of nephrotic syndrome." (PMID 37744450, 2023). "The patients were classified based on their response to steroid treatment, and the relationship between serum Leptin and CCL22 levels and steroid sensitivity in children with nephrotic syndrome was analyzed." (PMID 37744450, 2023). "This study aimed to compare patients with steroid-sensitive nephrotic syndrome (SSNS) and steroid-resistant nephrotic syndrome (SRNS) in terms of CCL22 and Leptin levels." (PMID 37744450, 2023).
neuroblastoma (1 paper, 2022). Neuroblastoma (NB) is the most common solid, extracranial childhood tumor. "In vitro, supernatants from DCs cocultured with neuroblastoma cell lines and activated contain CCL22 and CCL19, and are chemotactic for both CD4+ and CD8+ T cells." (PMID 36923280, 2022). "Altogether, these data suggest that CCL19 and CCL22 produced by activated DC play an important role in recruiting T cells to the neuroblastoma microenvironment in vitro and in vivo." (PMID 36923280, 2022). "To decipher which APC may be responsible for CCL19 and CCL22 secretions in neuroblastoma tumors, we analyzed correlations between these chemokine levels and APC-specific markers." (PMID 36923280, 2022). "Interestingly, CCL22 was found in supernatants of cocultured DC and neuroblastoma cells, but activation of DC was needed to induce CCL19 and T-cell migration in the same settings." (PMID 36923280, 2022). "On another hand, CCL22 was secreted by DC that were in contact with neuroblastoma cell lines, even in the absence of R848, and there was an additive effect of neuroblastoma cell lines and R848 on CCL22 production by DC." (PMID 36923280, 2022). "Altogether, our results suggest that CCL2 produced by neuroblastoma cells initiate the recruitment of monocytes, myeloid and plasmacytoid DCs, and that among these cells, the CD1c+ subset when activated may recruit T cells by means of CCL19/CCL22 secretion." (PMID 36923280, 2022). "Overall, our findings highlighted a major role for CCL2/CCR2 axis in monocytes, myeloid and plasmacytoid cells recruitment toward MYCN-nonamplified neuroblastoma, and suggest that the recruited myeloid DCs will further recruit T lymphocytes by means of CCL19 and CCL22." (PMID 36923280, 2022). "To confirm the involvement of CCL19 and CCL22 in T-cell migration, we analyzed CCL19 and CCL22 secretion by DCs (comprising PDC, cDC1, and cDC2), purified from healthy donors blood, that were cocultured for 24 hours in the presence or not of neuroblastoma cell lines and activated or not." (PMID 36923280, 2022). "In MYCN-nonamplified neuroblastoma, CCL2 produced by neuroblastoma cells induces the recruitment of antigen-presenting cells (DCs and monocytes/macrophages), allowing infiltration by T cells, in link with CCL19 and CCL22 production, hence favoring immune responses." (PMID 36923280, 2022).
osteoarthritis (1 paper, 2011). A noninflammatory degenerative joint disease occurring chiefly in older persons, characterized by degeneration of the articular cartilage, hypertrophy of bone at the margins and changes in the synovial membrane. "Another report has shown that CCL22 is present within the synovial membrane in rheumatoid arthritis and osteoarthritis patients and in high amounts in the synovial fluid of patients with rheumatoid arthritis and psoriatic arthritis." (PMID 22125604, 2011).
papilloma (1 paper, 2015). A benign epithelial neoplasm that projects above the surrounding epithelial surface and consists of villous or arborescent outgrowths of fibrovascular stroma. "The proposed mechanism of Treg recruitment is consistent with the data found in RRP which shows that CCL17 and CCL22 are produced by papilloma tissues and disseminated widely enough to be found in plasma." (PMID 26023354, 2015). "If it can be confirmed that LCs are the source of CCL17 and CCL22 in HPV 6 and 11-induced papillomas, it would suggest that LCs play an active role in creating and maintaining local immune suppression by recruiting T regulatory cells into HPV 6 and 11 infected epithelial tissues." (PMID 26023354, 2015).
parasite (1 paper, 2021). "The first exon of GRA28 is sufficient for induction of CCL22 during parasite infection of and ectopic expression in human cells." (PMID 34781732, 2021).
Pleural effusion (1 paper, 2025). The presence of an excessive amount of fluid in the pleural cavity. "ELISA analysis further confirmed that concentrations of CCL22 were significantly higher in MPE of LCP compared to pleural effusion of HP." (PMID 40959273, 2025).
polycystic ovary syndrome (1 paper, 2025). A disorder that manifests as multiple cysts on the ovaries. "Additionally, the identified biomarkers CCL22 may hold promise for future use as early screening biomarkers for polycystic ovary syndrome." (PMID 40181376, 2025).
prostate tumor (1 paper, 2020). "Further, in an ex vivo prostate tumor model, celecoxib suppressed intra-tumoral production of the Treg/MDSC-attractant CXCL12 and Treg-attractant CCL22, while increasing the production of the cytotoxic T lymphocyte (CTL) attractant CXCL10." (PMID 32824865, 2020).
psychosis (1 paper, 2020). "CCL22 levels are also associated with the core symptom domains of psychosis, and with altered patterns of adaptive/innate immunity signaling." (PMID 32179746, 2020). "Serum levels of chemokine CCL22 are persistently elevated in early psychotic disorders." (PMID 32179746, 2020). "Further studies are needed to characterize the relevance of high circulating CCL22 levels or enhanced CCR4 signaling for CNS function, as well as for the altered cyto/chemokine networks in psychotic disorders." (PMID 32179746, 2020).
rectal cancer (1 paper, 2021). A primary or metastatic malignant neoplasm that affects the rectum. "Radiation was found to have differential effects on normal rectal tissue and rectal cancer tissue with increased IL-15 and CCL22 secretion following radiation from normal rectal tissue explants (p < 0.05), while no significant alterations were observed in the irradiated rectal cancer tissue." (PMID 33540635, 2021).
renal carcinoma (1 paper, 2022). A carcinoma arising from the epithelium of the renal parenchyma or the renal pelvis. "The levels of CCL17 and CCL22 are also changed in renal cancer tissue, and the CCL17/CCL22 ratio in plasma is associated with poor prognosis." (PMID 36555280, 2022).
retinal degeneration (1 paper, 2022). Degeneration of the retina. "However, the role of Ccl22 during retinal degeneration, which does not involve T lymphocytes, is unknown, but it is likely involved in enhancing pathological inflammation." (PMID 36064575, 2022).
serous cystadenoma (1 paper, 2015). A serous neoplasm in which the cysts and papillae are lined by a single layer of cells without atypia, architectural complexity or invasion. "It is worth noting that, in patients with serous cystadenoma, in contrary to patients with EOC, levels of CCL22 were consistently higher in the plasma than in PF." (PMID 25647263, 2015).
skin atrophy (1 paper, 2025). The degeneration and thinning of the epidermis and dermis. "Meanwhile, prednisolone decreased the levels of histamine, IgE, CCL17, and CCL22 in plasma, but had adverse effects, such as lowering body weight, skin atrophy, and smaller spleens, compared to the NC." (PMID 39941059, 2025).
skin tumor (1 paper, 2021). "The skin tumor microenvironment contained potentially tumor-permissive myeloid cells producing regulatory (IDO1) and Th2-associated mediators (CCL13, CCL17, CCL22)." (PMID 33968070, 2021).
Splenomegaly (1 paper, 2015). Abnormal increased size of the spleen. "We observed a dramatic increase in the expression of several proinflammatory markers such as Il17a, Ifnγ, Tnfα, IL-1β and Ifitm1, and chemokines such as Ccl1, Cxcl10, Ccl22 and Xcl1, in ATMINΔLNBS1ΔL mice displaying splenomegaly, compared to the other genotypes." (PMID 26544571, 2015).
T-cell lymphoma (1 paper, 2019). "Since bexarotene significantly decreased expression of CCL22 mRNA in the tumor microenvironment, we hypothesized that bexarotene, as well as anti-CCL22 antibody (Ab) could suppress the growth of EL-4 T cell lymphoma in vivo." (PMID 31616630, 2019). "Both bexarotene and anti-CCL22 Ab significantly suppressed the growth of EL-4 T-cell lymphoma." (PMID 31616630, 2019). "Since intraperitoneal injection of bexarotene decreased expression of CCL22, CXCL5, and CXCL10 mRNA in EL4 mouse T-cell lymphoma, we hypothesized that serum levels of CCL22, CXCL5, or CXCL10 might be associated with response in CTCL patients treated with bexarotene." (PMID 31616630, 2019).
Thrombocytopenia (1 paper, 2015). A reduction in the number of circulating thrombocytes. "Notwithstanding, decreased serum CCL22 might also reflect the development of the thrombocytopenia observed in HPS cases." (PMID 26379668, 2015).
thyroid autoimmune diseases (1 paper, 2025). "Additional chemokines, such as CXCL10, CXCL9, CCL2, and CCL22, are expressed in both psoriatic and thyroid autoimmune diseases." (PMID 40863211, 2025).
tongue cancer (1 paper, 2021). A malignant neoplasm affecting the tongue. "A study conducted on tongue cancer suggests that high expression of CCL22 influences the balance of M1- and M2-like macrophages and leads to a deteriorated prognosis." (PMID 34391381, 2021).
tongue tumors (1 paper, 2021). "Therefore, we further validated the expression of Th1-associated chemokine genes, including Cxcl9, Cxcl10, and Ccl5, and Th2/Treg-associated chemokine genes, including Ccl17 and Ccl22, in carcinogen-induced tongue tumors using qRT-PCR." (PMID 33921389, 2021).